PRKCD (protein kinase C delta)
Description:
Calcium-independent, phospholipid- and diacylglycerol (DAG)- dependent serine/threonine-protein kinase that plays contrasting roles in cell death and cell survival by functioning as a pro-apoptotic protein during DNA damage-induced apoptosis, but acting as an anti-apoptotic protein during cytokine receptor-initiated cell death, is involved in tumor suppression as well as survival of several cancers, is required for oxygen radical production by NADPH oxidase and acts as positive or negative regulator in platelet functional responses. Negatively regulates B cell proliferation and also has an important function in self-antigen induced B cell tolerance induction (By similarity). In cytosol can trigger apoptosis by activating MAPK11 or MAPK14, inhibiting AKT1 and decreasing the level of X-linked inhibitor of apoptosis protein (XIAP), whereas in nucleus induces apoptosis via the activation of MAPK8 or MAPK9. Upon ionizing radiation treatment, is required for the activation of the apoptosis regulators BAX and BAK, which trigger the mitochondrial cell death pathway. Can phosphorylate MCL1 and target it for degradation which is sufficient to trigger for BAX activation and apoptosis. Is required for the control of cell cycle progression both at G1/S and G2/M phases. Mediates phorbol 12-myristate 13-acetate (PMA)-induced inhibition of cell cycle progression at G1/S phase by up-regulating the CDK inhibitor CDKN1A/p21 and inhibiting the cyclin CCNA2 promoter activity. In response to UV irradiation can phosphorylate CDK1, which is important for the G2/M DNA damage checkpoint activation (By similarity). Can protect glioma cells from the apoptosis induced by TNFSF10/TRAIL, probably by inducing increased phosphorylation and subsequent activation of AKT1. Is highly expressed in a number of cancer cells and promotes cell survival and resistance against chemotherapeutic drugs by inducing cyclin D1 (CCND1) and hyperphosphorylation of RB1, and via several pro-survival pathways, including NF-kappa-B, AKT1 and MAPK1/3 (ERK1/2). Involved in antifungal immunity by mediating phosphorylation and activation of CARD9 downstream of C-type lectin receptors activation, promoting interaction between CARD9 and BCL10, followed by activation of NF-kappa-B and MAP kinase p38 pathways (By similarity). Can also act as tumor suppressor upon mitogenic stimulation with PMA or TPA. In N-formyl-methionyl-leucyl-phenylalanine (fMLP)-treated cells, is required for NCF1 (p47-phox) phosphorylation and activation of NADPH oxidase activity, and regulates TNF-elicited superoxide anion production in neutrophils, by direct phosphorylation and activation of NCF1 or indirectly through MAPK1/3 (ERK1/2) signaling pathways. May also play a role in the regulation of NADPH oxidase activity in eosinophil after stimulation with IL5, leukotriene B4 or PMA. In collagen-induced platelet aggregation, acts a negative regulator of filopodia formation and actin polymerization by interacting with and negatively regulating VASP phosphorylation. Downstream of PAR1, PAR4 and CD36/GP4 receptors, regulates differentially platelet dense granule secretion; acts as a positive regulator in PAR-mediated granule secretion, whereas it negatively regulates CD36/GP4-mediated granule release. Phosphorylates MUC1 in the C-terminal and regulates the interaction between MUC1 and beta-catenin. The catalytic subunit phosphorylates 14-3-3 proteins (YWHAB, YWHAZ and YWHAH) in a sphingosine-dependent fashion (By similarity). Phosphorylates ELAVL1 in response to angiotensin-2 treatment. Phosphorylates mitochondrial phospholipid scramblase 3 (PLSCR3), resulting in increased cardiolipin expression on the mitochondrial outer membrane which facilitates apoptosis. Phosphorylates SMPD1 which induces SMPD1 secretion. Acts as a negative regulator of smoothened signaling by mediating phosphorylation of GLI1, preventing its localization to the nucleus.
Synonyms: PKCD; ALPS3; CVID9; MAY1; nPKC-delta
Tractability: Small molecule: an approved drug acts on it; a high-quality ligand is known; it belongs to a druggable protein family. Antibody: UniProt places it where antibodies can reach, with high confidence; its Gene Ontology location is reachable by antibodies, with high confidence. PROTAC: ubiquitination databases record sites on it; its protein half-life has been measured; a small molecule that binds it is known. Other modalities: a drug acting on it is in phase 2 or 3 trials.
Target class: AGC protein kinase group; Kinase; Enzyme; AGC protein kinase PKC delta subfamily; AGC protein kinase PKC family; Protein Kinase
Safety:
Unwanted effects reported when the protein is acted on. In parentheses: how it was acted on, where the effect was seen, and who reports it.
cardiac arrhythmia (cardiovascular system; source: Lamore et al. (2017))
Gene: Protein-coding gene on chromosome 3 (53,156,009 to 53,192,717, forward strand). Ensembl gene ENSG00000163932.
Subcellular location: Cytoplasm; Cytoplasm, perinuclear region; Nucleus; Cell membrane; Mitochondrion; Endomembrane system
Subcellular location (Human Protein Atlas): Cytosol; Endoplasmic reticulum; Golgi apparatus; Vesicles
Pathways (Reactome):
Signal Transduction: Calmodulin induced events; DAG and IP3 signaling; G alpha (z) signalling events; RHO GTPases Activate NADPH Oxidases; SHC1 events in ERBB2 signaling; VEGFR2 mediated cell proliferation
Immune System: CLEC7A (Dectin-1) signaling; Interferon gamma signaling; Neutrophil degranulation; Role of phospholipids in phagocytosis
Cellular responses to stimuli: KEAP1-NFE2L2 pathway
Hemostasis: Effects of PIP2 hydrolysis
Metabolism of RNA: HuR (ELAVL1) binds and stabilizes mRNA
Programmed Cell Death: Apoptotic cleavage of cellular proteins
Gene Ontology:
Molecular function: calcium,diacylglycerol-dependent serine/threonine kinase activity; diacylglycerol-dependent, calcium-independent serine/threonine kinase activity; enzyme activator activity; enzyme binding; protein binding; protein kinase activity; protein kinase binding; protein serine kinase activity; protein serine/threonine kinase activity; protein tyrosine kinase activator activity; diacylglycerol-dependent serine/threonine kinase activity; insulin receptor substrate binding; ATP binding; non-membrane spanning protein tyrosine kinase activity; protein tyrosine kinase activity
Biological process: apoptotic process; cell chemotaxis; cellular response to angiotensin; cellular response to hydrogen peroxide; cellular response to hydroperoxide; cellular response to UV; cellular senescence; DNA damage response; negative regulation of glial cell apoptotic process; negative regulation of inflammatory response; negative regulation of MAPK cascade; negative regulation of smoothened signaling pathway; neutrophil activation; peptidyl-serine phosphorylation; peptidyl-threonine phosphorylation; phospholipase C/protein kinase C signal transduction; positive regulation of ceramide biosynthetic process; positive regulation of DNA repair; positive regulation of glucosylceramide catabolic process; positive regulation of phospholipid scramblase activity; positive regulation of protein import into nucleus; positive regulation of sphingomyelin catabolic process; positive regulation of superoxide anion generation; protein phosphorylation; regulation of actin cytoskeleton organization; and 17 more
Cellular component: cytoplasm; cytosol; endolysosome; endomembrane system; endoplasmic reticulum; extracellular exosome; Golgi apparatus; mitochondrion; nucleus; plasma membrane; azurophil granule lumen; extracellular region; nucleoplasm; cell-cell junction; membrane; nuclear matrix; perinuclear region of cytoplasm
Genetic constraint (gnomAD): Loss-of-function variants: 20 observed, 84.48 expected, observed/expected ratio (o/e) 0.24, 90% interval 0.17 to 0.34. The upper end of that interval is the gene's LOEUF score, 0.34, which puts it in group 1 of 6, group 1 being the genes least tolerant of losing a copy. Missense variants: 604 observed, 926.63 expected, observed/expected ratio (o/e) 0.65, 90% interval 0.61 to 0.7. Synonymous variants: 311 observed, 350.17 expected, observed/expected ratio (o/e) 0.89, 90% interval 0.81 to 0.98.
Gene-disease validity (ClinGen):
ClinGen rates the evidence that PRKCD causes each of these diseases.
systemic lupus erythematosus (autosomal recessive): Definitive. An autoimmune multi-organ disease typically associated with vasculopathy and autoantibody production.
Homologues: Orthologues: chimpanzee PRKCD (99% identical), macaque PRKCD (93% identical), guinea pig PRKCD (91% identical), dog PRKCD (91% identical), mouse Prkcd (90% identical), pig PRKCD (90% identical), rat Prkcd (85% identical), tropical clawed frog prkcd (83% identical), zebrafish prkcdb (77% identical), zebrafish prkcda (77% identical), rabbit PRKCD (61% identical). Paralogues in human: PRKCQ (65% identical), AKT1 (28% identical), AKT3 (28% identical), AKT2 (27% identical), PDPK1 (19% identical).
Diseases named in the same sentence as PRKCD in open-access papers:
PRKCD is named in the same sentence as 102 diseases in open-access papers, as found by Europe PMC text mining. Sharing a sentence is not in itself a finding about the gene and the disease. The quoted sentences say what the papers report.
breast carcinoma (9 papers, 2016 to 2024). "Kaplan-meier analysis showed that high PRKCD expression was associated with poor survival, disease specific survival and distant metastasis free survival of breast cancer patients, especially for TNBC." (PMID 38347536, 2024). "PRKCD plays a dual role through autophagy, reducing the proliferation ability of breast cancer cells, which also regulating the self-renewal of cancer stem cells." (PMID 38347536, 2024). "For instance, PRKCD plays a role of tumor suppressor gene in breast cancer whereas it promotes tumor progression in pancreatic cancer." (PMID 34609335, 2021). "While PTPN14 is mutated in a number of cancers, increased PRKCD and RIN1 expression correlated with decreased overall survival in breast cancer, with the PRKCD correlation significant in the luminal A subtype." (PMID 27240404, 2016). "The levels of PRKCD and PRKCD_Y313 in breast cancer were validated in TCGA and CPTAC data." (PMID 38347536, 2024). "PRKCD has been shown to suppress breast cancer cell migration." (PMID 33925460, 2021). "PRKCD is not required for the proliferation or survival of normal cells, but it is required for proliferation of multiple types of cancer cells, both in vitro and in vivo, including those from cancers of the breast, pancreas and prostate as well as melanoma." (PMID 29088810, 2017).
colorectal cancer (5 papers, 2017 to 2024). A primary or metastatic malignant neoplasm that affects the colon or rectum. "In addition, PRKCD was validated to promote the invasion and migration of colorectal cancer cells, control stress fiber formation in melanoma, participate in the invasion of thyroid cancer, and cause persistent KIT activation in colon cancer." (PMID 38347536, 2024). "Moreover, magnolol used in the treatment of colorectal cancer reduces the phosphorylation of protein kinase C delta type (PKCδ) and NF-κB, which are two proteins that are involved in tumour progression in vitro and in vivo." (PMID 32717865, 2020).
hepatocellular carcinoma (5 papers, 2015 to 2025). A malignant tumor that arises from hepatocytes. "Additionally, in hepatocellular carcinoma, protein kinase C delta (PKCδ), which generally slows proliferation and induces cell cycle arrest of various cell lines, is found to suppress Hh signaling." (PMID 26512695, 2015).
Sepsis (5 papers, 2018 to 2024). Sepsis is defined as life-threatening organ dysfunction caused by a dysregulated host response to infection. "Survival analysis showed that PRKCD, EGLN1 and CFLAR were positively correlated with sepsis prognosis." (PMID 38997656, 2024).
systemic lupus erythematosus (5 papers, 2017 to 2024). "In addition, PRKCD polymorphisms are associated with increased risk of both systemic lupus erythematosus (SLE) and Crohn’s disease (CD)." (PMID 36782298, 2023). "Recently, a significant number of genes have been implicated in monogenic lupus, such as several complement deficiencies, ACP5, DNASE1, DNASE1L3, PRKCD, RAG2 genes, etc.." (PMID 34796153, 2021). "Protein kinase C delta (PKC-delta) deficiency is linked with defective B cell apoptosis and hyperproliferation and manifests as a systemic lupus erythematosus (SLE) phenotype." (PMID 28523402, 2017). "Protein kinase C delta (PKCδ) has emerged as a key protective molecule against systemic lupus erythematosus (SLE or lupus), an autoimmune disease characterized by anti-double stranded (ds) DNA IgGs." (PMID 38927570, 2024).
cervical cancer (4 papers, 2016 to 2024). A primary or metastatic malignant neoplasm involving the cervix. "Previous study confirmed that PRKCD was overexpressed in cervical cancer tissues, accompanied by the increased phosphorylation of E-cadherin at Thr790, which affected the EMT process." (PMID 38347536, 2024). "Transient over-expression of miR-181a confers resistance of cervical cancer cells to radiation therapy by targeting the pro-apoptotic PRKCD gene." (PMID 26754670, 2016).
diabetes (4 papers, 2015 to 2024). "Diabetes causes the inhibition of protein kinase C delta phosphorylation in neurons such as the dorsal root ganglia, slowing cell growth." (PMID 38927539, 2024). "For example, we speculate that the highly elevated upstream activities of CDK1 and PKCδ (represented by its catalytic subunit PRKCD) in the prediabetes stage may contribute to the development of diabetes." (PMID 35628588, 2022). "Circulating EVs from people with diabetes carry increased levels of specific phosphorylated kinases (i.e., AKT1, GSK3B, LYN, MAP2K2, MYLK, and PRKCD) and could potentially distribute activated kinases systemically." (PMID 35628588, 2022).
liver cancer (4 papers, 2021 to 2023). An epithelial or non-epithelial malignant neoplasm that arises from the liver. "Analysis showed that DCP1A was highly expressed in liver cancer tissues and its expression level was positively correlated with expression of PRKCD (P<0.05) in which was consistent with the findings using TCGA dataset." (PMID 34609335, 2021). "Our previous study identified E-Syt1 as a key factor for the unconventional protein secretion of cytoplasmic proteins in liver cancer, such as protein kinase C delta (PKCδ); however, it is unclear whether E-Syt1 is involved in tumorigenesis." (PMID 37241771, 2023).
autoimmune disease (3 papers, 2023 to 2025). A disorder resulting from loss of function or tissue destruction of an organ or multiple organs, arising from humoral or cellular immune responses of the individual to their own tissue constituents. "Protein kinase C like PRKCD is known to have a crucial role in the pathogenesis of autoimmune diseases like RA." (PMID 36983855, 2023). "Protein kinase C delta (PRKCD) and caspase recruitment domain family member 9 (CARD9) are genes involved in B and T cell activation, and cytokine production, which are vital mechanisms underlying autoimmune disease development." (PMID 36782298, 2023). "Sotrastaurin (a PRKCD inhibitor) is currently used to treat autoimmune diseases and tumors, but its therapeutic effect on HCC has not yet been observed." (PMID 40681503, 2025).
Autoimmunity (3 papers, 2018 to 2021). The occurrence of an immune reaction against the organism's own cells or tissues. "In addition, PRKCD has a negative role in T cell proliferation and a deficiency in PRKCD results in increased T cell activation contributing to T cell autoimmunity." (PMID 30459768, 2018). "All PRKCD, CTLA4, TET2 and NRAS/KRAS patients presented clinically with lymphoproliferation and autoimmunity, considering all those reported cases (n=197) as ALPS-like patients." (PMID 34447369, 2021). "However, only 100% of CTLA4, PRKCD, TET2 and NRAS/KRAS reported patients had an ALPS-like presentation, while the autoimmunity and lymphoproliferation combination resulted rare in other genetic defects." (PMID 34447369, 2021).
Insulin resistance (3 papers, 2016 to 2025). Increased resistance towards insulin, that is, diminished effectiveness of insulin in reducing blood glucose levels. "A previous study also demonstrated that free fatty acid-induced insulin resistance was associated with the suppression of protein kinase C delta (PKC δ) and downstream AKT." (PMID 27248994, 2016). "In addition, PRKCD is implicated in intracellular accumulation of ROS, leading to oxidative stress and insulin resistance in adipose tissues, while there is defective PRKCZ activity and glucose uptake (insulin resistance) in muscle and adipose tissues in T2DM cases." (PMID 40572705, 2025). "Increased levels of FFA, IHTG and the increased production of diacylglicerol and other lipotoxins activate protein kinase C-delta (PKC-δ) and nuclear factor kinase-B (NF-κB), leading to liver inflammation and insulin resistance." (PMID 31064058, 2019).
lung carcinoma (3 papers, 2009 to 2023). "Other genes that we chose (e.g., CD24, TACSTD1, TACSTD2, CEACAM1, and PRKCD) are correlated with lung carcinoma or other tumors." (PMID 19874631, 2009). "Our research suggests that PRKCD is an oncogene, and its high expression in lung cancer may promote cancer cell proliferation and migration." (PMID 38186574, 2023). "Korean researchers have shown that a heptapeptide of the protein kinase C delta (PKC-δ) catalytic V5 region binds to HSP27 in lung carcinoma NCI-H1299 cells, thereby impairing the HSP27-mediated tumor cell radioresistance in vitro and in the xenografts growing in mice." (PMID 33806538, 2021).
melanoma (3 papers, 2017 to 2024). A malignant, usually aggressive tumor composed of atypical, neoplastic melanocytes. "A previous study stated that PRKCD is required in primary tumor stem cell lines, including breast, pancreas, prostate, and melanoma cells, and is sensitive to depletion of PRKCD or inhibitors." (PMID 38347536, 2024). "In the present study, we first screened for any differences in the mRNA expression of the genes encoding these five PKC isozymes (PRKCD, PRKCA, PRKCB, PRKCE and PRKCI) between the BRAFi-sensitive and BRAFi-R melanoma cell lines." (PMID 36551563, 2022). "For example, PRKCD can be a suppressor in a few cancer types, but over-expression of PRKCD increased the metastatic potential of murine BL16 mouse melanoma cells." (PMID 29088810, 2017).
ovarian carcinoma (3 papers, 2021 to 2022). A malignant neoplasm originating from the surface ovarian epithelium. "MIR224 performs critical gene-regulating functions involved in chemoresistance in A2780CP/A2780S and C13/OV2008 ovarian cancer cells, via regulating the PRKCD (protein kinase C delta) pathway." (PMID 33920789, 2021). "Additionally, PRKCD has been regarded as a novel prognostic biomarker for ovarian cancer patient response to overall disease-specific survival." (PMID 35422861, 2022). "For instance, PRKCD (protein kinase C delta) is a member of protein kinase C (PKC) family which is a critical regulator of the chemosensitivity in cancers such as non-small-cell lung cancer, ovarian cancer, and prostate cancer." (PMID 35422861, 2022).